TUSC2 (tumor suppressor 2, mitochondrial calcium regulator)
Diseases named in the same sentence as TUSC2 in open-access papers (continued):
Sharing a sentence is not in itself a finding about the gene and the disease.
tumor (continued). "TUSC2 also downregulates the PD1/PD-L1 signaling in tumor cells." (PMID 35210547, 2022). "TUSC2 can inhibit mTOR activation and potentiate tumour sensitivity to AKT inhibitors in NSCLC." (PMID 31973107, 2020). "Emerging evidence suggests that restoration of TUSC2 could represent an attractive strategy to inhibit tumour growth and progression in cancer therapy." (PMID 31973107, 2020). "We also identify TUSC2, a tumour suppressor, as one of the direct targets of miR-138." (PMID 31481748, 2019). "Similarly, implantation of TUSC2 overexpressing cells yields tumours which are significantly smaller than those in the control group." (PMID 31481748, 2019). "We previously reported that restoration of TUSC2, a tumor suppressor gene in the 3p21.3 region that has been extensively characterized in 3p21.3-deficient NSCLC cells suppressed tumor growth by induction of apoptosis and alteration of cell kinetics in vitro and in vivo through Apaf-1." (PMID 29296193, 2017). "Several lines of evidence suggest this is related to expression of TUSC2 in the tumor." (PMID 22558101, 2012). "The TUSC2 protein was localized in the cytoplasm of tumor cells." (PMID 19852844, 2009). "In addition, forced expression of TUSC2 affected genes involved in cell cycle regulation, differentiation, and cell growth (0.01 < p < 0.0008) suggesting that TUSC2 possesses principal tumor suppressor properties." (PMID 19852844, 2009). "Finally, since hypoxia is one of the most common physiological conditions during tumor growth we sought evidence of TUSC2 hypoxic link." (PMID 19852844, 2009). "Therefore, we hypothesized that TUSC2 is involved in the regulation of PD-L1 signaling and the immune response in the tumor microenvironment." (PMID 29296193, 2017). "Therefore, down-regulation of TUSC2 in NK cells and other tumor-infiltrating lymphocytes by ROS may help cancer cells to escape immune suppression." (PMID 19852844, 2009). "In this study, we quantitatively assessed the expression levels of circ_RUSC2, miR-661, and TUSC2 mRNA in paired CRC tissues and adjacent non-tumor tissues and evaluated the correlation between their expressions and clinicopathological characteristics in CRC." (PMID 40243558, 2025). "The overexpression of miR-584-5p induced resistance to apoptosis by directly targeting the 3′UTR of TUSC2 mRNA (also known as FUS1), an important tumor suppressor downregulated in several human cancers." (PMID 39000555, 2024). "Silencing of miR-138 led to a significant increase in TUSC2 expression, promoted TNBC apoptosis, and prevented tumor growth in vivo." (PMID 37173921, 2023). "We have previously shown that the combination of TUSC2 and anti-PD1 inhibited tumor growth synergistically in subcutaneous and metastatic NSCLC KRAS mutant syngeneic mouse models." (PMID 35210547, 2022). "We also found six tumor related genes, TUSC2, TP53I3, TSSC4, RAB23, RAB39A, and ERG, which function as either tumor suppressor genes or oncogenes." (PMID 24007313, 2013). "In this report, we showed that the combination of TUSC2 transfection and MK2206 treatment suppressed tumor cell viability in vitro and effectively inhibited xenograft tumor growth in vivo more effectively than either agent alone." (PMID 24146957, 2013). "It has also been demonstrated that exogenous expression of TUSC2 using a nanoparticle-mediated gene transfer technique sensitizes NSCLC cells to cisplatin, resulting in a 4- to 6-fold increase in the TUSC2 tumor suppressor activity." (PMID 19852844, 2009). "Notably, the 3p chromosome change impacts over 500 genes, featuring tumor suppressors like BAP1, FHIT, VHL, PTPγ, SEMA3B, SEMA3F, TUSC2, and MLH1." (PMID 39201328, 2024).
tumor (continued). "TUSC2 nanovesicles combined with erlotinib, an inhibitor of activated epidermal growth factor (EGFR), synergistically inhibited tumor growth and metastases in NSCLC cells with wildtype EGFR by abrogating resistance pathways related to FGFR2 and mTOR activation." (PMID 27845352, 2016). "The majority of PTC samples were negative for TUSC2, suggesting a correlation between TUSC2 down-regulation and tumor progression." (PMID 27661106, 2016). "In term of tumor size, the posterior probability of cooperative effect was 0.9928, which means that there were less than 100 in 10,000 chances that the effect of TUSC2-erlotinib combination was not cooperative." (PMID 26053020, 2015). "In an orthotopic mouse model, the combination of TUSC2 and gefitinib also showed a marked reduction in tumor growth indicating that the effect was not restricted to erlotinib (data not shown)." (PMID 26053020, 2015). "In addition to the targets that we identified by RNA sequencing, miR-378a-5p has been shown to be involved in tumorigenesis and tumor maintenance by regulating SUFU, TUSC2, TOB2, GABPA and ESRRg." (PMID 24651706, 2014). "TXNIP, TUSC2, PPFIBP2, GALNT10 and MAP2K3 demonstrated varying degrees of methylation on their promoter regions in normal mucosa, normal salivary rinses and HNSCC tumor samples respectively." (PMID 23403885, 2013). "TUSC2 and MK2206 induced tumor cell apoptosis via activation of caspase-9, as shown by its cleavage, however, whether this caspase is an essential downstream component of this activity is yet to be determined." (PMID 24146957, 2013). "TUSC2, a tumor suppression gene, is completely absent or weakly expressed in the majority of NSCLC." (PMID 35210547, 2022). "The TUSC2P (tumor suppressor candidate-2 pseudogenes) promotes TUSC2 function by binding multiple microRNAs, and ectopic expression of TUSC2P and TUSC2 inhibits cell proliferation, survival, migration, invasion, and colony formation, and increases tumor cell death." (PMID 34120636, 2021). "We investigate that the TUSC2P was significantly down regulated in ESCC tissues and increased expression of TUSC2P might play a tumor repressive role in ESCC carcinogenesis by acting like ‘endogenous competitors’ of miRNAs, consequently de-repressed TUSC2 mRNA." (PMID 30219035, 2018). "Additionally, TUSC2 and TUSC2P expression showed highly correlation (r = 0.90, P < 0.001 and r = 0.85, P < 0.001, respectively) in both adjacent tissue and esophagus tumour samples, which suggests that they may be co-regulated in vivo." (PMID 30219035, 2018). "Ability of Fus1/Tusc2 to suppress receptor and non-receptor kinases as well as sensitize NSCLS cells to chemotherapeutics makes this tumor suppressor a promising therapeutic candidate for combinatorial therapy." (PMID 35181743, 2022).
cancer (24 papers, 2009 to 2025). A tumor composed of atypical neoplastic, often pleomorphic cells that invade other tissues. "Due to the prevalence of TUSC2 loss in many cancer types, investigations into therapeutic modalities that restore TUSC2 expression is a major topic of research." (PMID 37173921, 2023). "This review will focus on the current understanding of TUSC2 functions in both normal and cancerous tissues, mechanisms of TUSC2 loss, TUSC2 cancer therapeutics, open questions, and future directions." (PMID 37173921, 2023). "We previously showed that Tusc2-deficient mice display a complex immuno-inflammatory phenotype with a predisposition to cancer." (PMID 19852844, 2009). "We demonstrated earlier that Tusc2-deficient mice display a complex immuno-inflammatory phenotype with a predisposition to cancer." (PMID 19852844, 2009). "This section will discuss TUSC2 loss and its putative functions in other cancer types." (PMID 37173921, 2023). "Gene carriers delivering TUSC2 have been shown to interrupt cell signaling pathways that cause replication and proliferation of cancer cells, re-establish pathways for apoptosis, block drug resistance mechanisms, and modulate the immune response against cancer cells." (PMID 34727233, 2021). "Overall, these data imply that up to ~23% of cancer-associated TUSC2 targets may contribute to MPM progression and serve in future as novel therapeutic targets." (PMID 19852844, 2009). "Based on these data, we hypothesized that TUSC2 down-regulation may contribute to the development of human cancers associated with chronic inflammation." (PMID 19852844, 2009). "Our RNA-seq analysis of a GBM TUSC2-KO cell line revealed over 1200 differentially expressed genes in GBM, with Bcl-xL, a critical component in preventing intrinsic apoptosis in cancer cells, being one of the genes significantly upregulated upon TUSC2-KO." (PMID 37173921, 2023). "TUSC2 expression is commonly lost in many cancers due to somatic deletion, transcriptional downregulation, post-transcriptional downregulation, and post-translational regulation via the proteasomal degradation system." (PMID 37173921, 2023). "Overall, we found that ALKBH7, MYCBP, MZF1, RRS1, and TUSC2 were reported to be involved in the development and progression of cancer." (PMID 37654657, 2023). "When TUSC2 is re-expressed in these cancer types, it reduces cancer cell growth and promotes cell death." (PMID 37173921, 2023). "Tumor Suppressor Candidate 2 (TUSC2) is an important tumor suppressor that negatively regulates cancer growth and progression in multiple cancer types." (PMID 37173921, 2023). "Altogether, ALKBH7, MYCBP, MZF1, RRS1, and TUSC2 were reported to be involved in the development and progression of cancer, and dysregulation of these genes was known to be highly correlated with tumorigenesis." (PMID 37654657, 2023). "Numerous studies demonstrated that FUS1/TUSC2 overexpression in cancer cells that lack 3p21.3 or FUS1/TUSC2 gene/expression induces cell death." (PMID 35181743, 2022). "Rescue assays were carried out to confirm the contribution of tumor suppressor candidate 2 (TUSC2) in the aggressiveness of cancer cell which was regulated by miR-663." (PMID 30944041, 2019). "Numerous TUSC2-targeting miRNAs have been predicted by bioinformatics analysis and many targeting has already been validated, which indicating that TUSC2 abundance in cancer cells is largely dependent on post-transcriptional regulation." (PMID 30219035, 2018). "Tumor suppressor candidate-2 (TUSC2) is a novel tumor suppressor gene that found played important role in the pathogenesis of cancer." (PMID 30219035, 2018). "In the current study, microarray analysis using TUSC2-inducible cell lines and expression profiling indicated that TUSC2 overexpression led to AKT-mTOR pathway inhibition in cancer cells, which was associated with decreased PD-L1 levels." (PMID 29296193, 2017).
cancer (continued). "Measuring TUSC2 protein expression with various doses of Doxycycline treated cancer cells by western blotting indicated that TUSC2 proteins significantly increased upon Doxycycline treatments whilst β-actin remains unchanged." (PMID 27845352, 2016). "In this report, we found that addition of thioredoxin reductase 1 (TXNRD1) inhibitor auranofin to the TUSC2/erlotinib combination synergistically enhanced cancer cell death by induction of apoptosis through an increase in ROS." (PMID 27845352, 2016). "Since TUSC2 is a mitochondrial protein, our findings support an important role for mitochondria in the immune defense against cancer and bring to light previously unrecognized molecular components of mitochondrial immunity." (PMID 19852844, 2009). "FUS1/TUSC2 is a novel tumor suppressor located in the critical 3p21.3 chromosomal region frequently deleted in multiple cancers." (PMID 19852844, 2009). "The high expression of Tusc2 during mouse embryogenesis and, specifically, in mouse embryonic stem cells (ESC) suggests that TUSC2 has the potential as a cancer-causing gene." (PMID 19852844, 2009). "TUSC2 resides in the critical ~120 kb region that is often deleted in lung, breast, head and neck, renal, and other cancers." (PMID 19852844, 2009). "Additionally, TUSC2 has previously been shown to interact with two proteins important for regulating cancer progression and apoptosis, c-Abl and Apaf-1, respectively." (PMID 37173921, 2023). "TUSC2 is frequently lost in cancer due to somatic deletion within the 3p21.3 region, transcriptional inactivation via TUSC2 promoter methylation, post-transcriptional regulation via microRNAs, and post-translational regulation via polyubiquitination and proteasomal degradation." (PMID 37173921, 2023). "The cancer suppressive functions of TUSC2 have been previously identified in other cancers." (PMID 30944041, 2019). "TUSC2 is down-regulated in several human cancers and induces apoptosis." (PMID 27661106, 2016). "FUS1/TUSC2 may be hypermethylated in cancers of the head and neck, and decitabine may reverse this hypermethylation." (PMID 25024751, 2014). "We have recently investigated the possibility that transfect of the tumor suppressor gene TUSC2 in NSCLC cells deficient of its expression, could potentiate sensitivity to small-molecule targeted cancer therapy." (PMID 24146957, 2013). "However, it is possible that in other human cancers in which this deletion did not occur, other mechanisms cause a reduction in TUSC2 expression." (PMID 31973107, 2020). "Overexpressed TUSC2 in cancer cells could decrease Ca2+ distribution, and ATP production." (PMID 29296193, 2017). "Therefore, TUSC2 restoration could represent an important tool to arrest cancer cell proliferation." (PMID 31973107, 2020). "Rimkus, T., Sirkisoon, S., Harrison, A. & Lo, H. W. Tumor suppressor candidate 2 (TUSC2, FUS-1) and human cancers." (PMID 32358483, 2020). "For example, both tumour suppressor candidate 2 (TUSC2) 3′UTR and its pseudogene can inhibit cancer cell proliferation and survival via competitive binding of miRNAs which results in enhanced TUSC2 translation." (PMID 27561207, 2017). "Overall, our results imply that TUSC2 plays critical roles in cell cycle progression, cell differentiation, and immune system regulation, and that its downstream targets may provide important insights previously unknown molecular mechanisms and pathways involved in cellular defense against cancer." (PMID 19852844, 2009). "Since TUSC2 expression is inhibited by miRNAs across multiple cancer types, developing a nanoparticle carrying a TUSC2P expression vector may result in increased TUSC2 protein expression through sequestration of the TUSC2-targeting miRNAs." (PMID 37173921, 2023).
cancer (continued). "However, partial promoter methylation of the FUS1/TUSC2 gene was reported in head-and-neck as well as in 20% of NSCLC cancers." (PMID 35181743, 2022). "TUSC2 mediates apoptosis in cancer cells but not normal cells by upregulation of the intrinsic apoptotic pathway." (PMID 22558101, 2012). "To further investigate whether TUSC2 regulates PD-L1 at the transcriptional level, we measured PD-L1 mRNA levels in cancer cell lines after TUSC2 transfection with or without IFN-γ exposure." (PMID 29296193, 2017).
infection (1 paper, 2022). The state of being infected such as from the introduction of a foreign agent such as serum, vaccine, antigenic substance or organism. "In addition, Fus1/Tusc2-mediated anti-inflammatory and anti-aging activities provide avenues for development of new approaches to fight conditions of chronic inflammation, infections, premature aging and geriartic diseases." (PMID 35181743, 2022).
neurodegenerative disease (1 paper, 2024). A disorder of the central nervous system characterized by gradual and progressive loss of neural tissue and neurologic function. "Further investigation into these early processes will lead to a better understanding of the course of development of neurodegenerative diseases and possibly lead to Tusc2 or Tusc2-dependent processes being a therapeutic target for treating MCI/AD." (PMID 39000512, 2024).
TUSC2 also shares sentences with these, for which no sentence is quoted: sarcoma (3 papers); small cell lung carcinoma (2); Anxiety (1); asthma (1); head and neck tumors (1); hemangiosarcoma (1); lung adenocarcinoma (1); lymphoma (1); malignant mesothelioma (1); soft tissue sarcoma (1); thyroid (1).